BDH1 (3-hydroxybutyrate dehydrogenase 1)
Diseases named in the same sentence as BDH1 in open-access papers (continued):
Sharing a sentence is not in itself a finding about the gene and the disease.
tumor (continued). "Increased BDH1 expression in CD8+ T cells, which we observed in TILs from human tumours, facilitates greater βOHB oxidation in TILs as they infiltrate solid tumours." (PMID 41366157, 2025). "Given the reduction in Kbhb levels after BDH1 overexpression, the subsequent rise in Kbhb with the addition of Na‐BHB, and the noted tumor‐inhibitory effect of Na‐BHB, it can be inferred that BDH1 contributes to LUAD progression through Kbhb modification." (PMID 38098610, 2023). "Here we show the anti-tumor role of BDH1 in AML, which enlightens the possibility of restoration of BDH1 expression as an AML therapy." (PMID 34150668, 2021). "Together, we show the anti-tumor effects of BDH1 in AML, which indicate the therapeutic potential of targeting BDH1 to cure AML." (PMID 34150668, 2021). "The analysis showed that the expression of ACAT1, BDH1 and SLC16A1 was significantly higher in bone metastatic samples when compared with the primary tumor site (P = 0.0042, P = 0.0091, and P = 0.0006, respectively)." (PMID 34584218, 2021). "Collectively, our results suggest the previously unappreciated anti-tumor role of BDH1 in AML, and low BDH1 expression predicts poor survival." (PMID 34150668, 2021). "We reexamined the expression of BDH1 and OXCT1 in tumor tissues and found that these two genes were significantly upregulated." (PMID 29414764, 2018). "Ketone bodies are also major energy sources for mitochondria and they are synthesized in tumour stroma with the help of enzymes, such as HMGCS2, HMGCL, BDH1, and re-utilised in tumour cells." (PMID 28373964, 2017). "HNF4A interacts with proteins that are little characterised such as ACSS3, BDH1 and FDXR, and highlights the need for further functional investigations of these proteins in tumour pathogenesis." (PMID 24728830, 2014). "BDH1 and OXCT‐1 have been identified as potential neoplasm biomarkers; however, their mechanistic functions and therapeutic potentials in NB are unknown." (PMID 41420301, 2025). "BDH1 expression was unchanged and not significant in stage 4 tumours when compared to stage 1 NB in all datasets." (PMID 41420301, 2025). "The glycolytic genes, HK2, GAPDH and ENO1, were chosen as they mediate early, mid and final stages of glycolysis respectively, and all three ketolytic genes BDH1, OXCT1 and ACAT1 were analysed for MYCN amplification, survivability and tumour stage progression in three NB datasets." (PMID 41420301, 2025). "The main limitation of this study was the evaluation of other ketolytic enzymes including 3-hydroxybutyrate dehydrogenase 1(BDH1), 3-hydroxybutyrate dehydrogenase 2 (BDH2) and succinyl CoA: 3-oxoacid CoA transferase 1 (OXCT1) in the tumour and pre-tumour tissues of the OSCC patients." (PMID 36816175, 2023). "Finally, we detected BDH1 and OXCT1 expression levels in tumor tissue by qRT-PCR and immunohistochemistry." (PMID 29414764, 2018). "The use of BDH1 and OXCT1 inhibitors may enhance KD treatment efficiency and expand the anti-tumor spectrum of KD therapy." (PMID 29414764, 2018). "The HepaFH3 model recapitulated many features of tumor metabolism, including glycolytic activation and dedifferentiation, yet lacked key transformation markers such as c-MYC- and BDH1-driven ketone utilization." (PMID 40862732, 2025). "First, it does not address the impact of potential BDH1 inhibitors on LUAD migration, invasion, and tumor transplantation." (PMID 38098610, 2023).
cancer (15 papers, 2018 to 2026). A tumor composed of atypical neoplastic, often pleomorphic cells that invade other tissues. "BDH1 expression level is closely associated with the amount of ketone body in cancer cell lines." (PMID 34150668, 2021). "Beyond normal physiology, BDH1 functions as a context-dependent metabolic rheostat in human cancers, supporting altered neoplastic energy metabolism and conferring stress resistance." (PMID 42318484, 2026). "While research on BDH1 in cancer remains limited, several studies have highlighted its potential role." (PMID 40885386, 2025). "We showed that xenograft tumors that derive from cancer cells with low expression levels of BDH1 and OXCT1 are more responsive to KD therapy, likely because they possess weaker ability to metabolize ketone bodies." (PMID 29414764, 2018). "Based on the pRESs, the following amino acid changes were predicted in cancer tissue compared to adjacent normal tissue: K275R in BDH1, Q288E in CCDC137, and D44H in TBC1D10A." (PMID 30071094, 2018). "Here, we determined expression levels of genes encoding the ketolytic enzymes 3-hydroxybutyrate dehydrogenase 1 (BDH1) and succinyl-CoA: 3-oxoacid CoA transferase 1 (OXCT1) in 33 human cancer cell lines." (PMID 29414764, 2018). "Punit Saraon proposed that enzymes of the ketogenic pathway including BDH1 might be important biomarkers in tissue for the diagnosis or prognosis of high‐grade cancer." (PMID 36919822, 2023). "The expression levels of BDH1 vary among different cancer cells." (PMID 34150668, 2021). "The role of BDH1 and ketone body in cancer and cancer therapy still remains quite controversial." (PMID 34150668, 2021). "Further studies are necessary to determine whether other tumors derived from cancer cells with different expression levels of BDH1 and OXCT1 exhibit similar sensitivity to KD." (PMID 29414764, 2018). "Our results suggest that cancer cells with very low expression levels of BDH1 and OXCT1 may be sensitive to KD therapy." (PMID 29414764, 2018). "BDH1 promotes the malignant cell phenotype by mediating the H3K9bhb/LRRC31 axis, while BDH2 functions as an anti-cancer agent by facilitating cell autophagy and apoptosis." (PMID 39857793, 2025). "In this study, we report an aberrant overexpression of BDH1 in LUAD, which fosters the malignant phenotype of this cancer." (PMID 38098610, 2023). "This is due to deficiencies in succinyl-CoA:3-ketoacid coenzyme A transferase (OXCT1/SCOT), 3-hydroxybutyrate dehydrogenase 1 (BDH1) and acetoacetyl-CoA thiolase in cancer cell mitochondria." (PMID 37233716, 2023). "Cells with low levels of the ketolytic enzymes BDH1 and OXCT1 were more responsive to BHB and KDs in cancer cells in vitro and in vivo." (PMID 36432618, 2022). "Nevertheless, overall, our results suggest that expression of the key ketolytic enzymes BDH1 and OXCT1 is one of the main factors that determine the effect of a KD on cancer." (PMID 29414764, 2018). "The expression levels of the BDH1 and TBC1D10A genes were downregulated, while the CCDC137 gene was upregulated in cancer tissue compared to adjacent normal tissue." (PMID 30071094, 2018). "We investigated BDH1/2 and OXCT1/2 expression in several cancer cell lines and tested this hypothesis with two representative cell lines that had low and high expression levels of these key ketone body catabolism enzymes in vivo and in vitro." (PMID 29414764, 2018). "BDH1 and OXCT1 may be very useful biomarkers to determine the sensitivity of a particular cancer to a KD." (PMID 29414764, 2018). "Expression levels of BDH1/2 and OXCT1/2 mRNAs in 33 cancer cell lines were determined by qRT-PCR." (PMID 29414764, 2018).
metabolic disorders (4 papers, 2021 to 2024). "For example, Hmgcs2 and Bdh1, which are involved in ketogenesis, are upregulated by KD, suggesting a novel pathway for KD-ameliorated metabolic disorders." (PMID 38609395, 2024). "Previous research on BDH1 has primarily focused on normal organisms or metabolic disorders." (PMID 38098610, 2023). "HADHA overexpression improved metabolic parameter, and this effect was blocked by hepatic BDH1 knockdown, suggesting a role of BHB in regulating metabolic disorders." (PMID 35046401, 2022).
cardiovascular disease (2 papers, 2025). "Cardiac ketone body metabolism, beginning with BDH1-mediated breakdown of BHB, is thus a validated protective pathway in acute I/R injury and is beneficial in the context of human cardiovascular disease." (PMID 40161620, 2025).
kidney disease (1 paper, 2023). "Consistent with the DKD mouse model, we observed the downregulation of BDH1 in the renal tissues of diabetic patients with kidney disease using immunohistochemistry and IF staining." (PMID 38015723, 2023).
BDH1 also shares sentences with these, for which no sentence is quoted: ischemic cardiomyopathy (2 papers); Obesity (2); ovarian carcinoma (2); type 2 diabetes (2); atherosclerosis (1); brain tumors (1); cardiac diseases (1); cardiomyopathy (1); colon cancer (1); cystic kidneys (1); dilated cardiomyopathy (1); energy metabolism disorder (1); Heart (1); infection (1); infectious disease (1); lentivirus infection (1); liver cancer (1); liver fibrosis (1); lung adenocarcinoma (1); mild cognitive impairment (1); nasopharyngeal carcinoma (1); neuroblastoma (1); prostate carcinoma (1); schizophrenia (1); type 1 diabetes mellitus (1).